CRP (C-reactive protein)
Diseases named in the same sentence as CRP in open-access papers (continued):
Sharing a sentence is not in itself a finding about the gene and the disease.
tumor (continued). "The strong association between CA19-9 and CRP suggests that inflammation and tumour burden are closely intertwined in adenocarcinoma." (PMID 40332145, 2025). "Adding CEA further strengthened the model, allowing it to reach the highest adjusted R2 of 0.853 (p = 0.031), confirming the strong association between these tumour markers and CRP levels in patients with parietal fibrosis." (PMID 40332145, 2025). "The association between elevated CRP levels before treatment and tumor progression and decreased liver function in HCC has been reported in the literature." (PMID 40181742, 2025). "CRP reflects tumor-associated inflammatory activity and interleukin-6 levels, while serum albumin serves not only as an indicator of nutritional status but also as a surrogate marker of catabolic stress and physiological reserve." (PMID 40565984, 2025). "This divergence suggests that TNF-α (like CEA) is closely associated with tumor burden in advanced disease, while CRP—an acute-phase reactant—increases with inflammation more generally and less dramatically with stage." (PMID 40299527, 2025). "While numerous hematologic and composite inflammation indices were longitudinally assessed, CRP dynamics demonstrated potential prognostic value, dissociated from immediate radiologic tumor response but powerfully linked to long-term survival." (PMID 41267986, 2025). "There is also evidence that CRP is associated with the production of vascular endothelial growth factor, which plays an important role in tumor proliferation and invasion." (PMID 39963109, 2025). "We observed higher CRP levels with an increased depth of colonic wall invasion, likely due to the increased inflammatory response to the tumor associated with MSI CC." (PMID 39857073, 2025). "CRP is an established marker for disease activity and elevated CRP levels seem to be associated with advanced tumor stage and poor prognosis." (PMID 38254757, 2024). "Other studies have reported that the expression of CRP in tumor tissues is associated with the mass-forming gross type, absence of perineural invasion, and a better prognosis." (PMID 38881895, 2024). "Elevated CRP levels likely reflect ongoing inflammatory responses, while IL-6, a proinflammatory cytokine, has been implicated in tumor growth, angiogenesis, and immune evasion." (PMID 39816276, 2024). "In the validation cohort, intra-epithelial infiltration of the tumour by T-cells, especially T-helper 1 cells, was associated with high CRP levels." (PMID 39613865, 2024). "Interleukin-6 and C-reactive protein exhibit better diagnostic utility compared to traditional tumor markers in identifying OC, particularly in patients with OSCC." (PMID 38673838, 2024). "Both the primary tumor itself and the related inflammatory response cause cytokine production, and CRP production also increases." (PMID 38273418, 2024). "In this study, we found that C‐reactive protein (CRP) activates protumor functions of tumor‐associated macrophages." (PMID 39564003, 2024). "Both the primary tumor itself and the related inflammatory response are the cause of cytokine production, and the production of CRP will also increase." (PMID 38273418, 2024). "In the UCAN-validation cohort there was a significant association between high CRP levels and BRAF-mutated tumours, but a stratified analysis of CRP and MMR revealed a stronger association between CRP and MSI than with BRAF-mutation." (PMID 39613865, 2024). "Through multivariate Cox regression analysis, we found that SII, PNI, tumor size, tumor necrosis, surgical mode, pathological type, CRP, AJCC stage and Fuhrman grade were independent risk factors affecting the prognosis of patients with RCC (P < 0.05)." (PMID 39443568, 2024). "In the multivariate analysis, the incidence rate of COVID-19 pneumonia was associated with CRP, age, and tumor type." (PMID 38215120, 2024). "The association between CRP level and immune markers in tumour tissue and in blood was investigated." (PMID 39613865, 2024).
tumor (continued). "In contrast, the GNRI was significantly correlated with a lower BMI, lower SMI, lower albumin levels, higher CRP levels, a lower Child-Pugh Score A, more blood loss, longer postoperative hospitalization, and a larger tumor size." (PMID 38612974, 2024). "Associations between high preoperative CRP levels and molecular characteristics of the tumour were also explored." (PMID 39613865, 2024). "High CRP levels were also significantly associated with clinical factors implicated in tumor aggressiveness and development." (PMID 38172843, 2024). "Using CRP levels as a continuous variable and comparing these to tumour MMR status, higher CRP levels were associated with MSI tumours compared to MSS tumours, reaching significance in the U-CAN validation cohort." (PMID 39613865, 2024). "We also analysed The Cancer Genome Atlas Program (TCGA) data to link CD64 expression with ccRCC prognosis and used immunohistochemistry to associate CD64+ macrophages with tumor severity and systemic CRP levels." (PMID 39564003, 2024). "Chronic inflammation is associated with elevated COX-2 and CRP levels in tumor tissues, indicating a significant role of inflammation in disease progression." (PMID 39682667, 2024). "Our observation of a robust association between PF and the CRP/Alb ratio highlights the intricate interplay between the coagulation/fibrinolytic system and the inflammatory tumour microenvironment and suggests its potential to impact patient survival." (PMID 38496751, 2024). "High CRP levels were also significantly associated with clinical factors implicated in tumor aggressiveness and the development of OC." (PMID 38172843, 2024). "Skeletal muscle loss, serum AFP, and CRP levels have been identified as potential predictors of overall survival and tumor response in unresectable HCC patients undergoing the combination of TKIs and PD-1 inhibitors." (PMID 38698848, 2024). "The results from multivariate Cox regression analysis showed that SII, PNI, tumor size, tumor necrosis, surgical mode, pathological type, CRP, AJCC stage and Fuhrman grade were independent risk factors for postoperative death of patients with RCC." (PMID 39443568, 2024). "Elevated CRP and modified Glasgow Prognostic Score (mGPS) were associated with worse outcome and aggressive phenotype, similarly to tumor markers CEA and CA19-9." (PMID 38645565, 2024). "Body weight loss, muscle alteration, and high CRP/Mst levels were more prominent in B16F10 tumor-bearing mice." (PMID 37629186, 2023). "The tumor stage significantly modified the association between CRP-related indicators and the prognosis of chemotherapy patients." (PMID 36875131, 2023). "For instance, as well as being directly related to the tumor stage, glutamine levels have been inversely associated with serum C-reactive protein and inflammatory cytokines." (PMID 36855092, 2023). "Increased CRP levels are linked to the infiltration of immunosuppressive cells, including regulatory T (Treg) cells and tumor-associated macrophages, and thus predict undesirable outcomes in patients." (PMID 36998443, 2023). "Platelet count, CRP and neutrophil count (AUC 0.76 (p = 0.0078), 0.75 (p = 0.034) and 0.70 (p = 0.044), respectively) were associated with “N status” in dMMR tumours." (PMID 37493144, 2023). "The developed coupled tumor dynamics-biomarker model predicted circulating CRP concentrations and characterized the association between TS, a metric of tumor dynamics, and CRP, an inflammatory serum biomarker and a marker of disease aggressiveness." (PMID 38001689, 2023). "Univariate logistic regression analyses identified ECOG PS score ≥ 2, liver metastasis, tumor size ≥ 5 cm, neutrophils ≥ 69%, lymphocytes < 22%, sNLR ≥ 4, CRP ≥ 1 mg/dl, and albumin < 3.58 g/dl as significant risk factors for early death." (PMID 35871700, 2023).
tumor (continued). "Tumor-related factors can reflect tumor burden (metastatic sites, lactate dehydrogenase, C-reactive protein, and circulating tumor DNA) or can derive from the analysis of tumor samples (driver mutations, tumor-infiltrating lymphocytes, and myeloid cells)." (PMID 38201531, 2023). "In the present study, we found that CD4 + and CD8 + T cells distributed in different tumor areas were correlated with less aggressive tumor characteristics, but CRP distributed in different tumor areas were associated with more aggressive tumor features." (PMID 37277702, 2023). "A higher concentration of serum CRP was also associated with larger tumor size, the presence of lymph nodes and distant metastases, as well as more advanced stages of GC and worse survival rates of patients." (PMID 37240178, 2023). "An elevated CRP level reflects the inflammatory response caused by tumor necrosis and is significantly higher in metastatic colorectal cancer liver disease." (PMID 36980648, 2023). "In this real‐life study of survival with checkpoint inhibitor therapy for multiple tumour entities, we observed an independent association of pre‐treatment comorbidities, CRP and eosinophil count, and occurrence of irAE with improved overall survival." (PMID 37084178, 2023). "A multivariate analysis validated that the levels of H3Cit, IL-8 and CRP across treatment settings were significantly associated with the ICI response across four tumor types." (PMID 37580733, 2023). "CRP is an independent prognostic biomarker related to high tumor burden and associated with shorter OS and melanoma-specific survival." (PMID 38201531, 2023). "With respect to iBL over 1500 mL, low albumin level <4 g/dL, high CRP ≥ 0.2 mg/dL, and large tumor size were independent associated parameters by the multivariate analysis." (PMID 36980626, 2023). "In our study, although patients with LRP1B mutation had higher bTMB, CRP, PD-L1 positive rate, and larger tumor size, the association of LRP1B mutation with improved outcomes to ICI plus chemotherapy remained consistent after controlling for these factors." (PMID 35902848, 2022). "In this study, the serum CRP levels were associated with the tumor response, which was consistent with previous findings." (PMID 35965580, 2022). "Various blood examination-based nutritional parameters have been implicated in tumor prognosis (prognostic nutritional index, albumin-globulin ratio and c-reactive protein to albumin ratio)." (PMID 35729545, 2022). "It is to be noted that a low Hb level is associated with mortality independently from the tumor stage, age, gender, and C-reactive protein levels." (PMID 36140836, 2022). "As CRP is a non-specific marker of inflammation, other systemic inflammatory processes such as SIRS or neoplastic diseases can also cause an elevation in CRP similar to that in bacterial infections." (PMID 36713872, 2022). "We found that LRP1B mutation was associated with more PD-L1 positive, larger tumor size, higher CRP level, and bTMB value." (PMID 35902848, 2022). "An elevated CRP level seems to be an independent risk factor for shortened time to tumor progression." (PMID 34882287, 2022). "The presence of tumour-associated MMP-8-positive PMNs combined with a low CRP level also predicted a better survival." (PMID 35328734, 2022). "Persistent production of CRP reflects the signaling of the innate immune system, and increased CRP levels have been associated with tumor growth." (PMID 36293148, 2022). "Cut-off value = 0.68; CRP/Alb was associated with a more advanced tumor stage (P = 0.001), fewer patients with ideal cytoreductive surgery (P = 0.049), the presence of ascites (P = 0.009) and higher serum CA-125 level (P = 0.002)." (PMID 35464000, 2022). "At a higher threshold of 10 mg/L (used in the computation of GPS), there was evidence of an association between CRP and histology (p = 0.01) and tumor grade (p = 0.02)." (PMID 34802721, 2022).
tumor (continued). "First, the pre-infusion Total Metabolic Tumor Volume seems promising for its prognostic value, and should probably be associated with biological parameters, such as CRP at time of lymphodepletion." (PMID 34123825, 2021). "The level of CRP, reflecting inflammation, is regulated by interleukin (IL)-6 and IL-1β, which are associated with carcinogenesis, angiogenesis, and tumor growth." (PMID 34638613, 2021). "The highest level of serum CRP was exhibited in the group administered with zotarolimus combined with 5-FU, which was associated with the highest inhibition rate of tumor growth." (PMID 33925400, 2021). "Inflammatory markers levels are dependent on tumor types, but high level of CRP, IL-6, IL-1β have been associated with poor prognosis." (PMID 34867341, 2021). "To further characterize the association of serum CRP level and the immune status of the tumor microenvironment (TME) in HCC tissues, we analyzed gene expression microarray data of 24 HCC samples from our previous study." (PMID 35070979, 2021). "The densities of CD68+ tumor-associated macrophages (TAMs) and CD15+ tumor-associated neutrophils (TANs) were significantly higher in patients with elevated serum CRP levels than in those with low CRP levels (both p < 0.0001)." (PMID 35070979, 2021). "C-reactive protein (CRP) has been implicated in the pathogenesis of pNEN and shown to be associated with survival in different tumour entities." (PMID 34887479, 2021). "In the inoperable cohort, the high CRP level was associated with male sex, body weight loss and larger tumor size." (PMID 34350956, 2021). "They found that increased BMI was weakly associated with increased tumor thickness, and also with older age and increased log [CRP]." (PMID 34631264, 2021). "In turn, EPS were independently associated with tumor location (frontal or temporal lobe, P = .013) and pathologic laboratory values at admission (hemoglobin < 12 g/dL, [P = .044], CRP > 1.0 mg/dL [P = 0.036], and GGT > 55 U/L [P = 0.025])." (PMID 33506201, 2021). "The authors also suggest that high serum CRP levels are associated with more aggressive tumour characteristics such as larger tumour size and less differentiated tumours (G3)." (PMID 34887479, 2021). "The highest levels of serum IL-6, IL-10, and CRP were observed for the group administered with zotarolimus combined with 5-FU, and this was associated with the highest inhibition rate of tumor growth." (PMID 34361836, 2021). "An increase in preoperative serum CRP level was significantly associated with bigger tumours (p < 0.001)." (PMID 34887479, 2021). "The preoperative CRP levels showed the strongest associations with tumor stage (i.e., diameter; Kendall’s τ 0.315) and the presence of necrosis in the tumor (Kendall’s τ 0.332)." (PMID 32707675, 2020). "Among women with metastatic breast cancer, circulating tumor cells have been found to be associated with circulating C-reactive protein (CRP) and circulating interleukin-6 (IL-6), among other inflammatory markers." (PMID 33302472, 2020). "In our study, CRP was associated with tumor size and grading, suggesting a systemic measurable effect of pronounced host–tumor interactions." (PMID 32423000, 2020). "Specifically, this inflammation involves an increased activity of neutrophils and lymphocytes which secrete factors associated with tumor progression, such as C-reactive protein and albumin." (PMID 33276524, 2020). "Increased CRP is associated with patient factors (age, symptoms), as well as tumor characteristics (grading, tumor size) and OS." (PMID 32423000, 2020). "We thus investigated the association between survival and the IL33Rα level, CRP level, Leibovich score, tumor size, Fuhrman’s nuclear grading, ASA score, and age via univariate Cox prediction analyses." (PMID 32707675, 2020).
tumor (continued). "The male patients and high tumor stage were associated with elevated CRP levels (OR = 1.67, 95% CI: 1.34‐2.09; OR = 2.40, 95% CI: 1.44‐3.99), demonstrated by this meta‐analysis with low heterogeneity was low (I2 = 0.0%, p = 0.795; I2 = 64.3%, p = 0.038)." (PMID 33201589, 2020). "SAP and PTX4 share highly structural homology with CRP, but limited research has focused on their association with the tumor, similarly with the neuronal pentraxins." (PMID 33013829, 2020). "In the present study, the results of the biomarker analysis revealed that most factors related to PS and inflammatory biomarkers such as the NLR, LMR, LDH, and CRP levels were associated with the prognosis of tumour in patients treated with nivolumab." (PMID 33046752, 2020). "CRP levels have been reported to reflect the microenvironment and aggressiveness, such as tumor angiogenesis, in association with IL6." (PMID 32824226, 2020). "Our results correspond to previous reports on CRP in EC, where elevated serum CRP levels were associated with more aggressive tumor behavior, higher tumor development stages, and poor prognosis." (PMID 32977765, 2020). "Initial studies showed that the serum CRP levels had an expected prognostic association together with tumor size, stage, nuclear grading, and Leibovich score." (PMID 32707675, 2020). "CRP is directly associated with tumor mass and is believed to be induced by infiltrating lymphocytes and monocytes producing interleukins." (PMID 33316933, 2020). "To create a preoperative clinical risk score (CRS) allowing an estimate of postoperative patient survival, we combined three factors most strongly associated with OS in the multivariable model (CRP ≥0.2 mg/dL, presence of metastases, and tumor size ≥3 cm)." (PMID 32423000, 2020). "Of those patients receiving combined oxaliplatin therapy, an elevated CRP was associated with emergency presentation, T stage and differentiation (all p ≤ 0.001) and showed a trend towards more proximal tumour location." (PMID 32248375, 2020). "Herein, a novel interpretation of the diagnostic utility of CRP is presented accounting for the unique properties of the CRP isoforms in the context of the developing pro-metastatic tumor microenvironment." (PMID 33324413, 2020). "In this context, it has been shown that, among 102 patients with resected NSCLC, the preoperative CRP level was significantly associated with increasing tumor size corresponding to greater tumor load and poorer prognosis." (PMID 31936329, 2020). "Preoperative CRP is associated with unfavorable patient and tumor characteristics and independently predicts disease-associated survival in resected sporadic non-functional panNENs." (PMID 32423000, 2020). "Final models of logistic regression analysis for independent variables the PLR, NLR ratios and CRP/Glasgow index were then built to evaluate their associations with each of the four tumour parameters." (PMID 30662766, 2019). "Our previous studies demonstrated that pretreatment fibrinogen and CRP concentrations were associated with higher tumor stages and worse clinical outcome for TETs17." (PMID 31819103, 2019). "After matching, the univariate analysis showed that age (p < 0.001), TNM stage (p < 0.001), tumor site (p < 0.001), and preoperative serum CRP levels (p = 0.044) were significant risk factors for postoperative survival." (PMID 31533862, 2019). "In the present study, we found that serum CRP of 1 mg/dL or higher was associated with higher tumor recurrence in patients who underwent deceased donor LT for HCC." (PMID 31141535, 2019). "Proinflammatory cytokines, including interleukin-6, are produced by the tumor or surrounding cells and stimulate the production of acute-phase reactant proteins in the liver, such as CRP Therefore, CRP is associated with malignancy." (PMID 30974894, 2019). "Other risk factors, including advanced tumor stage, elevated CRP after treatment and CRP kinetics, were correlated with poor OS and DMFS rates." (PMID 30847301, 2019).